MYC (MYC proto-oncogene, bHLH transcription factor)
Diseases named in the same sentence as MYC in open-access papers (continued):
Sharing a sentence is not in itself a finding about the gene and the disease.
cancer (continued). "Furthermore, Gene Set Enrichment Analysis (GSEA) highlighted the effect of THZ531 on pathways of crucial relevance for many human cancers, including MYC target genes, epithelial-to mesenchymal transition (EMT) and mTORC1 signaling." (PMID 37202753, 2023). "The transcriptome and bioinformatics analyses revealed that the AR-V7 co-expression further altered the c-MYC-cancer cell-intrinsic biological processes, including proliferation, protein, and ribosomal biosynthesis, gene instability, and metabolism in hepatocarcinogenesis." (PMID 36746917, 2023). "The MYC regulatory network is one of the most frequently dysregulated networks in cancer." (PMID 37215074, 2023). "The MYC proto-oncogene contributes to the pathogenesis of more than half of human cancers." (PMID 37399401, 2023). "Recent studies have reported that both circRNA and MYC participate in cancer lipid reprogramming 15, 24, and thus we suppose whether circREOS can regulate lipid metabolism through MYC inhibition in OS." (PMID 37151387, 2023). "Amplification of MYC is observed in numerous of human cancers and is a frequent occurrence in prostate cancer (PCa), emphasizing its oncogenic function in this particular cancer." (PMID 37686488, 2023). "Research highlights the crucial role of c-MYC overexpression in this form of cancer." (PMID 38275631, 2023). "Using a small molecular chip assay, we found a selective MYC G4-binding drug with a benzofuran scaffold (D089) that can not only inhibit the expression of MYC in MM cell lines but also selectively induce G1 phase arrest in MYC-driven cancer cell lines containing the MYC G4 sequence." (PMID 37635159, 2023). "In this regard, CDCA7 may work as a regulator, downstream of MYC, and suppress the ferroptosis of cancer cells." (PMID 37510310, 2023). "Unexpectedly as well, the canonical mt-ISR based on eIF2α phosphorylation did not precede but followed the c-MYC upregulation, suggesting that mt-ISR is downstream of c-MYC, analogous to c-MYC-driven excessive anabolic metabolism leading to integrated stress response in cancer cells." (PMID 37095097, 2023). "Therefore, circRRM2/IGF2BP1/MYC formed a positive feedback loop and facilitated the invasion behavior of cancer cells." (PMID 36966311, 2023). "Moreover, MYC is known to drive the transcription of many ribosomal protein genes that are typically deregulated in various cancers." (PMID 37048063, 2023). "Since MYC drives enhanced nutrient uptake and biosynthesis across multiple cancer types, we hypothesized that MYC disruption of the molecular clock releases these processes from circadian control to instead be enhanced by amplified MYC." (PMID 37639465, 2023). "In cancer models where MYC is upregulated (by another oncogene or through circadian disruption), and is still circadian-controlled, MYC does not seem to exert a strong effect in suppressing BMAL1 and ablating rhythmicity of the molecular clock or downstream targets." (PMID 37639465, 2023). "MYC amplification universally corresponds with a worse prognosis across cancer types." (PMID 37130865, 2023). "Interestingly, in all of these studies, three TFs, namely SP1, HIF1A, and MYC, were among the factors that participated in the cancer regulatory network." (PMID 37998757, 2023). "The MYC oncogenes are involved in many cancers including hepatoblastoma." (PMID 37414763, 2023). "Collectively, our findings indicate that MYC-driven perturbations of the circadian clock release metabolic and biosynthetic processes from circadian control, potentially offering a metabolic advantage to cancer cells." (PMID 37639465, 2023).
cancer (continued). "Importantly, HIF2A-induced stabilization of MYC/MAX heterodimer is much stronger than HIF1A-mediated degradation of MYC in human cancer cells, leading to MYC activation under hypoxia." (PMID 37998757, 2023). "MYC, which is amplified by IGF2BPs, helps enhance the Warburg effect in cancers 61-63." (PMID 37554271, 2023). "CPEB family proteins are often downregulated in human cancers, so restoring their expression could lead to MYC inhibition in MYC-driven cancers." (PMID 37755397, 2023). "Additionally, YTHDF2 is very important for maintaining the growth of TNBC cells, which reduced the methylated transcripts in high-level transcription and translation processes in the cancer cells where higher MYC expression was observed." (PMID 37469704, 2023). "MYC is one of the most commonly dysregulated proto-oncogenes in cancer." (PMID 37400551, 2023). "MYC is a pleiotropic transcription factor involved in cancer, cell proliferation, and metabolism." (PMID 37105715, 2023). "MYC is one of the most deregulated oncogenes on multiple levels in cancer." (PMID 37443779, 2023). "To search for tumors in which regulation by the MYC promoter may be detectable as changes in mRNA abundance, we used cBioPortal for Cancer Genomics." (PMID 35887071, 2022). "The regulation of USP2-AS1 by MYC and HIF1α suggests that it might take part in the crosstalk between the MYC and HIF1α signaling pathways during cancer initiation and progression." (PMID 36359803, 2022). "MYC is one of the well-known oncogenes, and its important role in cancer still remains largely unknown." (PMID 36299592, 2022). "The combination of MYC 3′UTR shortening and the downregulation of miR-138 may contribute to increased MYC expression in cancer cells." (PMID 34937878, 2022). "Besides lncRNAs, circCD44 also directly interacts with IGF2BP2 to enhance the stability of c-MYC mRNA in m6A-modifed manner, promoting cancer progression in triple-negative breast cancer." (PMID 35541906, 2022). "In FGFR-aberrant cancers, MYC or CCND1 amplifications can indeed confer resistance to FGFRi48–50." (PMID 35948633, 2022). "In order to assess whether MYC also drives these changes in cancer cells, we examined these processes in two cell systems where MYC levels were lowered in MYC-driven cancer cell lines." (PMID 35945217, 2022). "A compound able to mimic this C-terminal MTBP peptide could serve as a small molecule inhibitor to target MYC oncogene addiction in many human cancers." (PMID 35741402, 2022). "However, MYC overexpression is detected in a majority of cancers and correlates with poor treatment outcomes." (PMID 35720131, 2022). "MYC expression is augmented in 60%–70% of cancers, and it is mainly regulated by BET proteins." (PMID 35401196, 2022). "The transcription factor c-MYC is essential for normal development and is a critical cancer driver." (PMID 35159073, 2022). "Furthermore, it has been also observed an increased expression of MYC, an essential transcription factor for regulating epithelial-mesenchymal transition and/or cancer stem cells." (PMID 36362083, 2022). "As the parent gene of circMGA, MGA could negatively regulate cancer cell proliferation and act as an inhibitor for MYC target genes; here in myoblast cells, circMGA shared the same repression on proliferation." (PMID 35405864, 2022). "Importantly, this study reveals that KMT5A-mediated SNIP1 K301 methylation not only serves as a key signal driving c-MYC hyper-activation and cancer metastasis, but also acts as a marker of poor prognosis of TNBC patients." (PMID 35449131, 2022). "c-MYC is an important oncogenic transcription factor in several cancers including TNBC." (PMID 36712364, 2022). "Stem cells and cancer-initiating cells are highly dependent on Wnt signaling, and therefore, our findings suggest that the bidirectional regulation of the clock and MYC could differ between stem cells and differentiated cells." (PMID 35947664, 2022).
cancer (continued). "Overexpression of MYC targets is cancer-derived and induced by copy number alteration." (PMID 35370699, 2022). "Thus, this in vivo experiment proved that loss of Senp6 accelerated MYC-driven B-cell lymphomagenesis in mice, providing direct experimental evidence that deregulated SUMO deconjugation accelerates cancer formation." (PMID 35022408, 2022). "Alternatively, it could imply different cancer cell lines maintain expression of MYC targets through differing means, which imparts distinct dependencies." (PMID 36577800, 2022). "Expression of the c-MYC (MYC) proto-oncogene is deregulated in over 50% of all cancers." (PMID 36139061, 2022). "Diverse mechanisms of aberrant MYC pathway activation in human cancers were identified." (PMID 35512017, 2022). "MYC, acting as a transcription factor, and a slight disturbance of MYC expression may promote cancer cell evolution." (PMID 36299592, 2022). "In addition, our pan-cancer analysis showed that RIPK2-induced activity scores are strongly (rho = 0.88 on average) correlated with MYC activity scores across all the 32 cancer types." (PMID 35115556, 2022). "The potent repressive effect of miR-138 on MYC expression in cancer cell lines led us to hypothesize that it may also have a significant effect on MYC-driven carcinogenesis in vivo." (PMID 34937878, 2022). "Besides harboring MYC, dysregulation and amplification of which is found in many human cancers, the 8q24.21 locus also harbors lncRNA PVT1 53 kb downstream of MYC." (PMID 35820706, 2022). "Aberrant activation of MYC in cancer has been extensively studied." (PMID 36578501, 2022). "Furthermore, studies suggest that MYC overexpression can promote field cancerization, which is thought to be a cancer-initiating event in which tissue regions are altered to promote increased proliferation." (PMID 36139061, 2022). "Increased lncRNA PVT1 expression is required for MYC protein upregulation in human cancer cells." (PMID 36118202, 2022). "Considering the ubiquitous nature of ZNF148 expression, the MYC, ZNF148, ID1/3 regulatory axis may be present in a broad array of cancers driven by MYC and ID proteins." (PMID 36207293, 2022). "JNK activation-mediated constitutive elevation of MYC expression may represent a novel mechanism governing cancer cell sensitivity to TOP1-targeting therapy." (PMID 35844787, 2022). "Importantly, aberrant MYC expression has been described to induce resistance to chemotherapy in general, and paclitaxel in particular, in breast and other cancers." (PMID 36860495, 2022). "As MYC-driven cancers suppress the autocrine secretion of factors mediating senescence or immune cell invasion, combining the insights from targeting MYC at the protein level and activating the immune surveillance could define future therapies." (PMID 36611833, 2022). "Yet these examples, involving alterations in chromosomal architecture, underestimate the true frequency with which MYC is dysregulated in cancer as aberrant signaling by many mutant growth factor pathways converge on MYC and promote its over-expression in the absence of structural changes." (PMID 35203395, 2022). "Besides, oxidative phosphorylation, unfolded protein response, MYC targets, and MTORC1 signaling were also tightly associated with PDIA3 expressions in cancers." (PMID 35401558, 2022). "Furthermore, oncogenic splicing factors such as hnRNPA1 and hnRNPA2 can also be induced by MYC to sustain a high level of PKM2/PKM1 ratio in cancer cells." (PMID 36319992, 2022).
cancer (continued). "While in normal cells that are not actively growing, this process happens only under hypoxic conditions, in the cancer cell, through activation of oncogenes such as MYC and PI3K/AKT signaling, this happens even in normoxic conditions, hence the term aerobic glycolysis." (PMID 36077530, 2022). "A recent study demonstrated that MYC interacts with cancer stem cells and thus exerts an important role in regulating the initiation of BC, suggesting it may serve as a predictor of BC diagnosis." (PMID 36418345, 2022). "Further, GSVA unraveled that many cancer hallmarks were dysregulated between these two groups, with a noticeable pattern of an enrichment of proliferation pathways (e.g. E2F targets, G2M checkpoint and MYC targets) in the mutant group." (PMID 35350771, 2022). "Expectedly, many MYC target genes are essential for cancer cell fitness." (PMID 36577800, 2022). "Comparison of whole transcriptome RNA sequencing analysis in patients with HER2+ and HER2− identified unique immune-related pathways including macrophage activation, and T-cell response as well as cancer-related pathways including Wnt signaling and MYC-related pathways." (PMID 36612126, 2022). "The gain of function of the 8q24 region, harboring MYC, is a frequent variation in various cancers." (PMID 36052265, 2022). "More importantly, we found a significant increase in the SCNAs encompassing genes from the PI3K and RAS pathways, compared to other cancer genes, in the context of MYC amplification or gain in the TCGA cohorts (TCGA breast cohort p-value = 0.0001; TCGA lung cohort p-value<0.0001)." (PMID 36289203, 2022). "Therefore, the mechanism behind MYC regulation is a viable therapeutic target for the treatment of cancer." (PMID 35887071, 2022). "In present study, we reported that IFITM3 served as a novel modulator of HGF/MET-mediated AKT signaling that suppressed FOXO3 (Forkhead Box O3), consequently leading to c-MYC (MYC proto-oncogene) mediated cancer proliferation, migration, stemness and drug resistance." (PMID 35941699, 2022). "Moreover, the oncogenic transcription factor c-MYC is reported to be able to stimulate glutamine metabolism by upregulating GLS to support the growth of cancer cells." (PMID 36611819, 2022). "MYC was also found to co-amplify with PVT1 in several cancer cell lines." (PMID 36761693, 2022). "c-Myc is an important oncogene that contributes to carcinogenesis, and approximately 28% of human cancers have amplified MYC paralogs, which could be an attractive target for drug development." (PMID 36362068, 2022). "In addition, in cancer cells, G4 can be converted back into duplex DNA, thanks to the action of highly expressed Topo enzymes, thus activating c-MYC transcription." (PMID 36428499, 2022). "As such, the inhibition of MYC has been established as a powerful anti-cancer strategy in vivo." (PMID 36018850, 2022). "The activation of MYC is considered a biomarker of cancer initiation and maintenance." (PMID 35370699, 2022). "MYC is recognized as one of the most frequently amplified oncogenes in human cancers." (PMID 36319992, 2022). "BRD3 may affect cancer prognosis by controlling the expression of oncogenes, such as MYC, in a similar manner to BRD4." (PMID 34605158, 2022). "Thus, targeting MYC activity seems to be a promising strategy to treat MYC‐driven, and possibly other types of cancer." (PMID 36214609, 2022). "The oncoprotein MYC is a potent driver of many human cancers." (PMID 35204714, 2022). "MYC overexpression in cancer was accompanied by remodeling of the glycerophospholipid metabolism." (PMID 36611833, 2022).
cancer (continued). "Given that transactivation of MYC through the NF-κB pathway induces cell proliferation and cell cycle promotion in a variety of cancer cells, our observations may provide a mechanistic explanation to overcome paclitaxel resistance." (PMID 35194034, 2022). "Among these biomarkers, STAT3 and MYC can influence cancer cell survival and promote proliferation." (PMID 35743172, 2022). "Our study provides novel insight into the biochemical process underlying T-ALL metabolic reprogramming and facilitates a rational selection of adjunctive metabolic therapy in combination with CPI-613 to treat MYC-driven T-ALL and perhaps other MYC-driven cancers as well." (PMID 35740646, 2022). "So with a slight MYC expression disorder, it is possible to promote cancer cell evolution." (PMID 36299592, 2022). "Multilayer buffering systems may also require targeting more than 1 PRMT to tackle MYC-driven cancers, a further consideration that needs to be extended in the future in more detail." (PMID 35439169, 2022). "Indeed, CNA at the 8q24.21 locus, which contains the MYC gene, is common in many cancers, including CRC." (PMID 36139061, 2022). "Frequent RIPK2 and MYC co-amplification/gain also occurs in several other cancer types." (PMID 35115556, 2022). "For example, astaxanthin treatments may suppress the mobility and dissemination of cancer tissue by a decrease in MYC transcription factor mediation." (PMID 35276890, 2022). "The MYC oncogene is amplified or deregulated in the majority of human cancers." (PMID 36860495, 2022). "MYC, one of the most frequently investigated proto-oncogene, has been reported as one of the most highly amplified oncogene contributes to the initiation and development of many human cancers." (PMID 36505846, 2022). "In cancer, BRD4 has been implicated in the activation of a multitude of oncogenes, co-occupying a set of promoter super-enhancers associated with prominent oncogenic drivers such as c-MYC." (PMID 35681619, 2022). "Moreover, focal CNA amplifications encompassed genomic peaks that harbored canonical cancer genes including those found at HPV-integrated hotspots (MYC, MYCN, MYCL, SOX2, NR4A2, and ANKRD12), and others (CCNE1, SMAD2, BCL2L1, and GNAS)." (PMID 36216793, 2022). "c-MYC is another oncogenic transcription factor being involved in crucial processes such as metabolic reprograming, extracellular matrix remodeling, inflammation, and regulation of a variety of malignant features in cancer." (PMID 36483040, 2022). "Whether this class of drugs would be an effective treatment for MYC‐driven cancer remains to be systematically addressed." (PMID 36214609, 2022). "A substantial fraction of cancers shows high MYC pathway activity without MYC copy gain but with mutations in genes with noncanonical roles in MYC." (PMID 35562349, 2022). "Reciprocally, oncogenic MYC imparts a series of molecular and metabolic dependencies to cells, thus giving rise to cancer‐specific vulnerabilities that may be exploited to obtain synthetic‐lethal interactions with novel anticancer drugs." (PMID 36214609, 2022). "MYC increases intracellular levels of tryptophan and tryptophan metabolites in the canine uridine metabolic pathway, thereby meeting the needs of the rapid proliferation of cancer cells." (PMID 35281118, 2022). "c-MYC overexpression is a driver of cancer and drug resistance." (PMID 35267559, 2022). "Importantly, MYC is often amplified in cancer and the mechanism of MYC over-expression in Drosophila is amplification." (PMID 36291770, 2022). "Because cancer cells need MYC to grow, MYC is usually overactive in human cancers." (PMID 35741402, 2022). "Importantly, MYC overexpression not only drives cancer growth, but it also induces oncogenic transformation, chemoresistance and disease relapse." (PMID 35625675, 2022).